CTLA4 (cytotoxic T-lymphocyte associated protein 4)
Diseases named in the same sentence as CTLA4 in open-access papers (continued):
Sharing a sentence is not in itself a finding about the gene and the disease.
Sepsis (continued). "Notably, CTLA-4 inhibitor treatment specifically provided survival benefits in this subgroup of mice, suggesting a potential strategy for precise treatment of alcohol-related sepsis." (PMID 41209006, 2025). "The findings above imply that CTLA4 accumulation is accompanied by impaired autophagy and increased mTOR signaling pathway activity, there may be a regulatory link between mTOR, autophagy, and CTLA4 accumulation that impacts CD4+ T cell manifestation in sepsis." (PMID 39104632, 2024). "It has been documented that PD-1 and CTLA-4 might be associated with the severity and control of sepsis by upregulating Treg cells and that increasing CD39+Treg was associated with a poor prognosis for sepsis in adult patients." (PMID 39072327, 2024). "Moreover, investigating the interplay between TIM-3 and other immune checkpoint molecules, such as PD-1 and CTLA-4, may yield valuable insights into potential combination therapies for sepsis." (PMID 38576606, 2024). "Additionally, the observation that lactate elevates the expression of PD-1 and CTLA-4 in Treg cells may provide insights into whether lactate should be measured in clinical trials of immune checkpoint inhibitors for sepsis." (PMID 39372401, 2024). "Therefore, it is possible that the presence of specific CTLA-4 SNPs could be beneficial during sepsis in regard to alleviation of CTLA-4 mediated T cell exhaustion." (PMID 33613563, 2020). "Therefore, CTLA-4 levels could define acquired immunity status in sepsis." (PMID 41153671, 2025). "First, CTLA-4, PD-1, CD39, Integrin α4β1, and integrin α4β7 on Treg were assessed in patients with sepsis." (PMID 39072327, 2024). "CTLA-4 antibody treatment attenuates sepsis-induced cell death, preserves numbers, and improves survival in CLP sepsis models." (PMID 39104632, 2024). "Previous studies have found that co-inhibitory molecules, such as PD-1, CTLA-4, LAG-3, VISTA, are upregulated during sepsis, we then queried the expression of TIGIT and its ligand CD155 upon sepsis insult." (PMID 38545097, 2024). "The study revealed a significant upregulation of cytotoxic T lymphocyte antigen-4 (CTLA-4), TIM-3, and LAG-3 receptors on T lymphocytes in individuals with acute sepsis." (PMID 38576606, 2024). "CTLA-4 is also highly expressed in CD4 T cells, CD8 T cells, and/or inhibitory receptors in monocytes from patients with sepsis." (PMID 38114466, 2023). "We found in sepsis that the A2aR antagonist ZM241385 inhibited Treg expansion, CTLA-4 and Foxp3 expression, secretion of IL-10 and TGF-β and inhibitory activity on T-cell proliferation." (PMID 36148230, 2022). "Therefore, the T cell protective effects of therapeutics blocking immune checkpoints such as PD-1 and CTLA-4 pathways during sepsis could also involve metabolic reprogramming and re-invigoration of the glycolytic pathway, which will be an interesting topic for future studies." (PMID 33613563, 2020). "CTLA-4 acts to oppose CD28 which is a critical regulator of early T cell activation and proliferation, and CTLA-4 is found to be upregulated on CD4+, CD8+ and Tregs following sepsis." (PMID 33336293, 2020). "Thus, it remains to be established whether PD-1 and/or CTLA-4 are also induced by critical injury alone prior to septic infection, like BTLA, or whether they act in a more redundant manner during sepsis to cause further dysfunction and/or apoptotic loss of these cells." (PMID 24289156, 2013). "CD15+CD14+ monocytes, CD45RA−17A+CD4+ T cells, CD45RA−CX3CR1+CTLA4+CD4+ T cells, and Ki67+ B cells were significantly increased in patients with sepsis, with the CD15+CD14+ monocytes having the largest normalised effect size in sepsis." (PMID 40433376, 2025). "Immunomodulatory cytokines (IFN-γ, IL-7, -15, -33), growth factors (GM-CSF), thymosin-α, immune checkpoint inhibitors (PD-1/PD-1L, CTLA-4, LAG-3, TIM-1), administration of immunoglobulins, and cell therapy with mesenchymal cells are being studied for use in patients with sepsis." (PMID 40566028, 2025).
Sepsis (continued). "Immune checkpoint inhibitors, including anti-PD-1 and anti-CTLA-4 antibodies, have revolutionized cancer treatment and are now being explored in sepsis to reverse immune paralysis and restore immune function." (PMID 40563999, 2025). "In patients with sepsis and SAI, non-survivors had higher CTLA-4 expression than survivors (sepsis: 427.5 versus 130.6, P=0.002; and SAI: 506.7 versus 225.2, P<0.0001)." (PMID 39104530, 2024). "Similarly, in murine models of septic peritonitis, investigators have not only shown CTLA-4 expression to increase following cecal ligation and puncture (CLP), but also that administration of low-dose anti–CTLA-4 mAb improves sepsis mortality." (PMID 38226924, 2024). "We can conclude from our studies that the shifts in Treg and Tconv following Ctla4 deletion are not dependent on either alcohol intake or sepsis alone, because the control groups are exposed to alcohol and are septic." (PMID 38226924, 2024). "The finding that anti–CTLA-4 improves sepsis survival in alcohol-drinking but not water-drinking mice is an interesting and potentially unexpected observation." (PMID 38226924, 2024). "The expression of CTLA-4 on CD4+ lymphocytes significantly correlated with LC3II expression in patients with sepsis, patients with SAI, and non-surviving patients with SAI." (PMID 39104530, 2024). "The expression of CTLA-4 significantly correlated with that of LC3II in patients with sepsis, patients with SAI, and non-surviving patients with SAI." (PMID 39104530, 2024). "The expression of CTLA-4 statistically correlated with that of LC3II in patients with sepsis, patients with SAI, and patients with SAI who did not survive (correlation coefficient: 0.69, 0.68, and 0.73, respectively, P<0.0001)." (PMID 39104530, 2024). "Measurement of CTLA-4 expression in the CD4+Foxp3− Tconv (CD4+ Tconv), CD4+Foxp3+ Treg (CD4+ Treg), and CD8+ T cell compartments of these mice after alcohol exposure and tamoxifen administration followed by CLP verified decreased CTLA-4 expression on both CD4+ Tconv and CD4+ Treg during sepsis." (PMID 38226924, 2024). "Dot plot of these genes in sepsis single-cell data revealed the CD8+ T cell exhaustion subcluster (TS3 with high CD8+ T cell markers CD8a, CD8b, and exhaustion markers PDCD1 and CTLA4)." (PMID 37077915, 2023). "In the cell-type RNA-Seq dataset, we found that CTLA4 was mainly expressed on CD4+ T cells but not CD8+ T cells, and CTLA4 was significantly up-regulated in sepsis." (PMID 37077915, 2023). "The main classes of drugs used for the evaluation of sepsis treatment are immunostimulatory drugs (immune targets CSF2RA/B, CSF3R), immunostimulatory cytokines (immune target is IFNGR1/2), and immunosuppressants (PDL1 and CTLA4)." (PMID 36389695, 2022). "Numerous studies of sepsis in adults have shown increases in percent Tregs and Treg activity (as measured through cytokine expression of IL-10 and TGF-β and as expression of CTLA-4 and FOXP3 on the cell surface) and implicate Tregs in adaptive immune suppression." (PMID 35958579, 2022). "The immune checkpoints such as CTLA-4, PD-1/PD-L1, TIM-3, and LAG-3 are all found to be upregulated on T cells in murine sepsis models, and these coinhibitory molecules have emerged as fundamental targets for reversing sepsis-induced immunosuppression." (PMID 34366711, 2021). "An increased expression of negative T-cell co-stimulatory molecule (PD1, CTLA4) was described in both cancer and candida-related sepsis revealing possible immunological similarities." (PMID 34417900, 2021). "In fact, multiple emerging issues and molecules are noted with critical involvement in sepsis and host immune response, covering inhibitory immune cells, neuro-endocrine immune networks, as well as negative immunomodulatory molecules, such as CTLA-4 and PD-L1." (PMID 31892843, 2020).
Sepsis (continued). "Treatment with anti-CTLA4 antibody attenuates T cell apoptosis and improves survival in CLP induced sepsis (using a dose of 50 μg per mouse) and in a two-hit model of CLP induced sepsis followed by fungal infection with C. albicans (using a dose of 50 μg per mouse)." (PMID 33613563, 2020). "An important feature of immunosuppression is T cell exhaustion, which was recently recognized following many trials for sepsis involving immunoregulatory therapies, such as PD-1 blockade, interleukin 7 administration, interleukin 15 administration, IFN-γ administration, and CTLA-4 blockade." (PMID 31440257, 2019). "To examine their participation in immune regulation, we aimed to measure plasma concentrations of the soluble isoforms of PD-1, CTLA-4 and BTLA in critically ill patients and evaluate their usefulness as sepsis biomarkers and indicators of severity of disease and prognosis." (PMID 28056053, 2017). "Accumulated evidence has shown that a combination of Foxp-3, CTLA-4, TGF-βm+, and inhibitory cytokines (IL-10 and TGF-β) might serve as active markers for Tregs in the process of sepsis." (PMID 27835904, 2016). "In addition, Tregs strongly upregulated the markers CTLA-4, CD69 and CD25, indicating that they were activated within hours after sepsis induction." (PMID 23724126, 2013). "Individually, higher frequency of CD15+CD14+monocytes [0.83 (95%CI 0.71,0.94)], CD45RA-CX3CR1+CTLA4+CD4+ T cells [0.77 (95%CI 0.64,0.90)], CD45RA−17A+CD4+ T cells [0.76 (95% CI 0.61,0.90)], and Ki67+ B cells [0.76 (95%CI 0.64, 0.88)] yielded good AUROC for distinguishing sepsis from healthy." (PMID 40433376, 2025). "In addition, the expression of FOXP3, CTLA4, TIGIT, TNFRSF18, and IL2RA, key functional genes of Tregs, was increased in the E-SEP group, suggesting that the immunosuppressive effect of Tregs was enhanced in the elderly with sepsis." (PMID 38909272, 2024). "Moreover, checkpoint inhibition of CTLA-4 improved sepsis survival in alcohol-drinking septic mice, but not water-drinking septic mice." (PMID 38226924, 2024). "However, the role of T cell coinhibitory molecules, specifically CTLA-4, in the setting of chronic alcohol exposure and sepsis has not been explored." (PMID 38226924, 2024). "However, we cannot conclude that the shifts in Treg and Tconv after Ctla4 deletion in alcohol-exposed septic mice would not still occur in the absence of either alcohol exposure or sepsis." (PMID 38226924, 2024). "Notably, the analysis identified potential mediators of sepsis-induced immunosuppression, including Arg-1, SOCS-1, and SOCS-3, which were highly upregulated in multiple cell types and negative costimulatory molecules, including PD-1 and CTLA-4 upregulated in sepsis." (PMID 37317092, 2023). "Compared with non-immunosuppressed patients with sepsis, patients with SAI had a higher 28-day mortality rate (37.5% vs 13.0%, P=0.039) and higher CTLA-4 mean fluorescence intensity (MFI) on CD4+ T cells (328.7 versus 78.7, P<0.0001)." (PMID 39104530, 2024). "Given the observed survival benefit of anti–CTLA-4 in alcohol-drinking, but not water-drinking, septic animals, we sought to identify the cellular source of CTLA-4–mediating sepsis pathogenesis in alcohol-drinking mice." (PMID 38226924, 2024). "When compared within the sepsis group or SAI group, CTLA-4 MFI on CD4+ lymphocytes from non-survivors was also significantly higher than that from survivors." (PMID 39104530, 2024). "The MFI of CTLA-4, LC3II, mTOR, and P62 on CD4+ cells were significantly higher in patients with sepsis than in non-septic patients (185.5 versus 104.4, P<0.0001; 152.3 versus 99.6, P=0.001; 166.8 versus 143.6, P=0.029; and 244.0 versus 177.2, P=0.001, respectively)." (PMID 39104530, 2024). "In addition, the percentage of CD4+ cells expressing CTLA-4 and CTLA-4 MFI on CD4+ cells were also higher among non-surviving patients with sepsis (90.2% versus 50.3%, P<0.0001; and 427.5 versus 130.6, P=0.002, respectively)." (PMID 39104530, 2024).
Sepsis (continued). "The expressions of CTLA-4 and FOXP3 were significantly higher in patients with serious burns at all time points, and they were even higher in septic patients than those without sepsis on PBD 3 to 21 (P < 0.01)." (PMID 20064232, 2010). "Although the number of Treg was not altered after sepsis, a higher number of Treg expressing inhibitory markers was noticed, specifically a higher number of KLRG1+ Treg in CLP compared to SHM animals, and a higher number of PD-1+ and CTLA-4+, but not of KLRG1+ Treg in CLP+STZ compared to SHM+STZ." (PMID 41142792, 2025).
sarcoma (69 papers, 2011 to 2025). A usually aggressive malignant neoplasm of the soft tissue or bone. "Although monotherapy with an anti-PD-1 antibody and combination therapy with cytotoxic T-lymphocyte associated protein 4 (CTLA-4) antibodies have shown anti-tumour activity in advanced sarcomas, the response rate remains modest less than 20%8,9." (PMID 38263321, 2024). "Using mouse sarcoma models to investigate the mechanisms of action for ICIs, one group found that antibiotic treatment abrogated the antitumor effects of anti–CTLA-4 therapy." (PMID 39895632, 2025). "Nivolumab (anti-PD-1 antibody) monotherapy and in combination with ipilimumab (anti-CTLA-4 antibody) was evaluated by the phase II Alliance trial in locally advanced, unresectable, or metastatic sarcomas." (PMID 40075735, 2025). "The first pediatric phase I trial of the CTLA-4 antibody, ipilimumab, included patients less than 21 years with R/R refractory solid tumors (17 patients with sarcomas)." (PMID 38140246, 2023). "Despite these findings, use of monotherapy ICB (antibodies against PD-1, PD-L1 or CTLA-4) in sarcoma has traditionally shown poor efficacy, dependent on the sarcoma histologic subtype." (PMID 36765578, 2023). "Anti-PD-1 antibodies as monotherapy in combination with anti-CTLA-4 antibodies have shown antitumor activity against advanced sarcomas, although the proportion of patients who achieve a response remains modest." (PMID 37233406, 2023). "Pseudotime trajectory analysis on scRNA-seq data from intra-tumoral NK cells isolated from mouse sarcomas revealed that the expression of perforin and granzymes were induced by anti-CTLA-4 treatment." (PMID 35326731, 2022). "In mice, a reduction in MCA205 sarcoma was observed during anti-CTLA-4 therapy when Bacteroides fragilis, Bacteroides thetaiotamicron and Burkholderia species were present in their organisms." (PMID 36428677, 2022). "Immunotherapy with immunological checkpoint inhibitors (ICIs), cytotoxic T lymphocyte-associated antigen-4 (CTLA-4), programmed cell death protein-1 (PD-1), and PD-ligand 1 (PD-L1) have demonstrated impressive clinical efficacy in patients with sarcoma." (PMID 34979500, 2022). "For instance, PD-1 or CTLA-4 inhibition has been reported to synergize with the blockade of adenosine metabolism to inhibit tumor growth in colon cancer and sarcoma mouse models." (PMID 36713558, 2022). "Since monotherapy with PD-1 or CTLA-4 inhibitors showed modest improvement in sarcoma patients’ survival, novel combinations with cytotoxic agents, anti-angiogenic agents, etc., are undergoing active investigation to induce consistent and durable responses." (PMID 34277600, 2021). "With these results, immune checkpoint blockade targeting cytotoxic T lymphocyte-associated antigen 4 (CTLA-4) and programmed cell death protein 1 pathway (PD-1/PD-L1) have been investigated and tested in the treatment of sarcoma." (PMID 33946044, 2021). "Combined regimens based on immune checkpoint inhibitors (anti-PD1 or anti-CTLA4) and modified T-cell therapies are currently being tested in specific sarcoma subtypes with a significant clinical benefit for the patients." (PMID 34277600, 2021). "Combination therapies can also be efficient in these tumor types as demonstrated by the success of combining monoclonal antibodies targeting PD-1 and CTLA-4 in angio- and other sarcoma types." (PMID 32141029, 2020).